SMARCB1 (SWI/SNF related BAF chromatin remodeling complex subunit B1)
Diseases named in the same sentence as SMARCB1 in open-access papers (continued):
Sharing a sentence is not in itself a finding about the gene and the disease.
rhabdoid tumor predisposition syndrome (24 papers, 2008 to 2025). "A genetic form of AT/RTs known as rhabdoid tumor predisposition syndrome, which is typically sporadic but can be inherited in an autosomal dominant manner, is caused by mutations in the integrase interactor 1 (INI1) gene (also known as SMARCB1) at 22q11.23." (PMID 39677208, 2024). "The timing of the acquisition of a SMARCB1 mutation can have a major impact on which type of tumor develops, as evidenced by the initial discovery of SMARCB1 mutations in both rhabdoid tumor predisposition syndrome and familial schwannomatosis." (PMID 37173979, 2023). "In fact, LOH of chr22 or chr22q was a ubiquitous event observed in all tumors within our cohort and is likely the most common mechanism for a second hit in SMARCB1 in patients with rhabdoid tumor predisposition syndrome (i. e., germline SMARCB1 mutation)." (PMID 35912263, 2022). "Rhabdoid Tumor Predisposition Syndromes (RTPS) are characterized by heterozygous germline PVs leading to inactivation of SMARCB1 (commonly) or SMARCA4 (rarely) which are inherited in an autosomal dominant fashion." (PMID 33532948, 2021). "Familial cases described as the rhabdoid tumor predisposition syndrome, have been linked to heterozygous SMARCB1 germline mutations." (PMID 34777208, 2021). "Germline mutations in SMARCB1 are responsible for rhabdoid tumor predisposition syndrome and familial schwannomatosis." (PMID 32380731, 2020). "Germline mutation of the SMARCB1 gene results in a phenotype known as the “rhabdoid predisposition syndrome,” which increases the risk of developing renal and extrarenal rhabdoid tumors." (PMID 32328470, 2020). "A consistent fraction of cases carries de-novo SMARCB1/INI1 constitutional mutations in the setting of the “rhabdoid tumor predisposition syndrome” and the outcome is worst in infant syndromic ATRT patients." (PMID 23510391, 2013). "We here describe a patient affected by mosaic Klinefelter syndrome and by rhabdoid tumor predisposition syndrome caused by constitutional SMARCB1/INI1 heterozygous mutation c.118C>T (Arg40X)." (PMID 23510391, 2013). "A small percentage of AT/RT cases occur due to the loss of SMARCA4, another core member of the SWI/SNF chromatin remodeling family; moreover, single inherited mutations of either SMARCB1 or SMARCA4 contribute to rhabdoid tumor predisposition syndrome (RTPS) 1 or 2, respectively." (PMID 34945804, 2021). "The constitutional pathogenic variant in SMARCB1 causes rhabdoid tumor predisposition syndrome." (PMID 34777208, 2021). "Germline mutations of the SMARCB1 gene predispose to two distinct tumor syndromes: rhabdoid tumor predisposition syndrome, with malignant pediatric tumors mostly developing in brain and kidney, and familial schwannomatosis, with adulthood benign tumors involving cranial and peripheral nerves." (PMID 28824165, 2017). "Notably, a consistent fraction of cases carries de-novo SMARCB1/INI1 constitutional mutations in the setting of the so called “rhabdoid tumor predisposition syndrome”." (PMID 23510391, 2013). "Preserved INI1 protein expression and a SMARCA4 mutation were also observed in familial rhabdoid tumor predisposition syndrome (RTPS), which has been linked to heterozygous SMARCB1 germline mutations." (PMID 26109171, 2015). "Due to the lack of routine copy number assessment in constitutional patient DNA, constitutional copy number variations of SMARCB1 were not reported in two patients with AT/RT and a known rhabdoid tumor predisposition syndrome where data were suggestive of a heterozygous deletion." (PMID 36928815, 2023).
glioma (21 papers, 2016 to 2025). A benign or malignant brain and spinal cord tumor that arises from glial cells (astrocytes, oligodendrocytes, ependymal cells). "While SMARCB1 is not yet a formal requirement for glioma classification in WHO CNS5, a loss of SMARCB1 function is increasingly recognized in pediatric and early-onset gliomas." (PMID 40564017, 2025). "Atypical teratoid/rhabdoid tumor (ATRT) is an aggressive central nervous system tumor characterized by loss of SMARCB1/INI1 protein expression and comprises three distinct molecular groups, ATRT–TYR, ATRT–MYC and ATRT–SHH." (PMID 35501487, 2022). "Atypical Teratoid Rhabdoid Tumor (AT/RT) is a rare pediatric central nervous system cancer often characterized by deletion or mutation of SMARCB1, a tumor suppressor gene." (PMID 34145313, 2021). "Identification of HML-2 expression as a marker of AT/RT following the loss of SMARCB1 is a primary step in establishing the role of endogenous retroelements in this central nervous system tumor development." (PMID 34145313, 2021). "A recent study in mice has shown that inactivation of Smarcb1 can most efficiently cause tumors resembling atypical teratoid/rhabdoid tumours (AT/RTs), an agressive pediatric CNS cancer, when induced during an early window of pre-natal development (E6 to E10)." (PMID 27296804, 2016). "However, it remains to be explored whether SMARCB1 implicated in the proliferation and migration of glioma cells." (PMID 32420340, 2020). "SMARCB1, which encodes SNF5, is well-known for its tumor suppressor function across multiple cancers including pediatric CNS cancers and sarcomas." (PMID 38472198, 2024). "AT/RT is a malignant tumor of the central nervous system characterized by the deletion of the SMARCB1 (INI1) gene on chromosome 22q11.2." (PMID 36913010, 2023). "In this regard, we further reasoned that MEG3 mediates miR-6088, which in turn regulates SMARCB1 in glioma cells." (PMID 32420340, 2020). "Collectively, MEG3 can hinder cell migration and proliferation of glioma cells via modulating miR-6088/SMARCB1 axis." (PMID 32420340, 2020). "Herein, we can draw a conclusion that MEG3 regulates cell growth of glioma cells through mediating the miR-6088/SMARCB1 axis." (PMID 32420340, 2020). "The aberrant profile of lncRNA-MEG3 and SMARCB1 in glioma cells indicates their implication in glioma progression." (PMID 32420340, 2020). "Consistently, our findings uncover that SMARCB1 is downregulated in glioma cells and contributed to the suppression of cell migration and proliferation of glioma cells." (PMID 32420340, 2020). "Collectively, the evidence in this study indicated that MEG3 was downregulated in glioma cells and inhibited proliferation and migration of glioma cells via regulating miR-6088/SMARCB1 axis." (PMID 32420340, 2020). "Altogether, these findings indicate that the overexpression of MEG3 can inhibit glioma cell progression, while the overexpression of miR-6088 or the inhibition of SMARCB1 can partially reverse the inhibitive effect of pcDNA3.1-MEG3 on glioma cells." (PMID 32420340, 2020). "The 2016 WHO Classification of Tumors of the Central Nervous System defined AT/RT by alterations of either INI1 protein (SMARCB1 gene), or rarely, BRG1 protein (SMARCA4 gene)." (PMID 30547013, 2018). "This indicates that SMARCB1 may play a critical role in glioma’s early development and presentation." (PMID 40564017, 2025). "MEG3 and SMARCB1 expressions were downregulated in glioma cells." (PMID 32420340, 2020). "Therefore, we aim to explore the possible role of MEG3 and SMARCB1 in glioma cells and to further clarify the mechanism herein." (PMID 32420340, 2020). "Transfection of miR-6088 mimic or si-SMARCB1 could obviously reverse the favorable effect of pcDNA3.1-MEG3 on glioma progression." (PMID 32420340, 2020). "This study further investigated the function of SMARCB1 on glioma cells." (PMID 32420340, 2020).
glioma (continued). "Therefore, we conjectured that MEG3 may regulate certain intermediate to affect SMARCB1 in glioma cells." (PMID 32420340, 2020). "In this work, we found downregulated MEG3 and SMARCB1 in glioma cells, but no direct interaction of MEG3 and SMARCB1 was identified." (PMID 32420340, 2020). "Altogether, these results revealed that miR-6088 mimic and SMARCB1 silencing could partially rescue pcDNA3.1-MEG3 induced EMT and migration of glioma cells." (PMID 32420340, 2020). "As we proved that both MEG3 and SMARCB1 are implicated in glioma cells, no direct interaction is found between MEG3 and SMARCB1." (PMID 32420340, 2020). "Herein, SMARCB1 inhibits cell migration and EMT of glioma cells." (PMID 32420340, 2020).
brain tumors (19 papers, 2008 to 2025). "This pediatric brain tumor occurs due to the biallelic inactivating mutations of the SMARCB1 (SWI/SNF related, Matrix Associated, Actin Dependent Regulator of Chromatin, subfamily B, member 1) gene in chromosome 22." (PMID 38496035, 2024). "Next, we extended our investigation to include an RNA-seq dataset comprising primary brain tumors, covering both SMARCB1-wildtype brain tumors and SMARCB1-deficient ATRTs." (PMID 39472584, 2024). "Until now, two families have been described in which the development of these malignant childhood brain tumours correlated with the inheritance in two or more generations of a mutation in the INI1/hSNF5/BAF47/SMARCB1 gene on chromosome 22." (PMID 18087273, 2008). "Collectively, our findings from both the primary brain tumor cohort and the I2A cell line suggest that the SMARCB1 deficiency may prime ATRTs for the induction of viral mimicry, a response that can be further enhanced upon EZH2 inhibition." (PMID 39472584, 2024). "All tumors, however, showed complete loss of nuclear SMARCB1/INI1 protein expression and were unequivocally classified as ATRT–SHH using the Heidelberg Brain Tumor Classifier [median calibrated classifier score: 1.00 (Classifier version 12.3)]." (PMID 35501487, 2022). "Definition of ATRT: ATRTs are embryonal brain tumors histologically characterized by cells with rhabdoid features and molecularly characterized by biallelic inactivation of SMARCB1 or SMARCA4." (PMID 33415075, 2020). "Indeed, differential expression analysis revealed that ATRTs exhibit higher expression of retroelements, particularly Alu elements, compared to SMARCB1-wildtype brain tumors." (PMID 39472584, 2024). "Additionally, the total expression of IR-Alu repeats was computed, demonstrating an overall increased expression in ATRTs compared to SMARCB1-wildtype brain tumors." (PMID 39472584, 2024). "Unlike most pediatric brain neoplasms, AT/RTs are in terms of genetic alterations intersimilar and nearly all cases present with deletion and/or mutation of the tumour suppressor gene SMARCB1 (INI1/hSNF5) located on chromosome 22 which results in loss of SMARCB1 protein expression." (PMID 26998479, 2015). "A total of 29 relevant brain tumor genes are indicated on the graph and notably PTEN and MGMT are located on chromosome 10 whereas SMARCB1 and NF2 are located on chromosome 22." (PMID 40136376, 2025). "We suggest that adult AT/RT may not be markedly dissimilar to other adult brain tumors where mutations in a range of genes, reflecting the functional specialization of different brain regions, but including SMARCB1 inactivation, may be required for its pathogenesis." (PMID 26557502, 2015).
lung carcinoma (18 papers, 2014 to 2025). "Due to the extreme rarity of SMARCB1/INI-1-deficient lung carcinoma, a comprehensive literature review identified eight previously reported cases." (PMID 40291911, 2025). "Lung cancer remains the leading cause of cancer-related mortality globally, with genes such as SMARCB1, MEOX2, and GLI-1 playing significant roles in its malignancy." (PMID 39971779, 2025). "After determining a SMARCB1-Driven EGFR expression in lung cancer, we examined if this association had an impact on EGFR-TKI resistance." (PMID 39971779, 2025). "This outcome suggests that the loss of SMARCB1 may enhance the activation of compensatory cancer signaling pathways, allowing A549 lung cancer cells to evade the inhibitory effects of this anti-cancer compound “afatinib”." (PMID 39971779, 2025). "SMARCB1-deficient lung carcinomas (INI1 loss) rarely exhibit EGFR mutations." (PMID 40291911, 2025). "SMARCB1 has been noted in STK11 deficient de-differentiated lung cancer." (PMID 39125735, 2024). "SMARCB1 loss has been described in lung cancer as isolated case reports." (PMID 39125735, 2024). "This evidence let us confirm SMARCB1 as a tumor suppressor in lung cancer and prompted us to investigate lung cancer progression and response to the EGFR-TKI-afatinib at in vivo (nu-/nu-) mice model." (PMID 39971779, 2025). "Our analysis revealed a significant increase in tumor growth in the shSMARCB1 (vehicle experimental group) compared to the shSCR control, further supporting SMARCB1 tumor-suppressive role in lung cancer." (PMID 39971779, 2025). "In conclusion, this study reveals the critical roles of MEOX2, GLI-1, and SMARCB1 as tumor biomarkers in human lung cancer progression." (PMID 39971779, 2025). "Nonetheless, despite its significant involvement in different malignancies, the specific function of SMARCB1 in lung cancer remains underexplored." (PMID 39971779, 2025). "The association between SMARCB1 and EGFR significantly influenced lung cancer cell sensitivity to EGFR-TKI-afatinib, evident in both in vitro and in vivo settings." (PMID 39971779, 2025). "Based on this, we conducted Co-IP assays using A549 lung cancer cells, which revealed that SMARCB1 interacts with MEOX2, GLI-1, and BRD9, with a potential weak interaction with CBP and EZH2." (PMID 39971779, 2025). "So, this study aimed to evaluate the expression profiles of lncRNA GIAT4RA, lncRNA AATBC, lncRNA Sirt1-AS, and SMARCB1 in lung cancer." (PMID 39313797, 2024). "As a result, this study assesses the expression profiles of lncRNA GIAT4RA, lncRNA AATBC, lncRNA Sirt1-AS, and SMARCB1 genes in lung cancer patients." (PMID 39313797, 2024). "Moreover, SMARCB1 downregulation seems to be an uncommon finding in primary lung cancer, as well as the immunophenotypic and morphological resemblance to SMARCB1-deficient carcinoma of the sinonasal tract, indicates that pulmonary SMARCB1-deficient carcinoma could be a distinct diagnostic entity." (PMID 39313797, 2024). "SMARCB1 expression was significantly downregulated in chronic inflammatory patients, while in those with lung cancer, it showed an insignificant difference." (PMID 39313797, 2024). "Further investigation of SMARCB1 revealed its potential tumor suppressor role in lung cancer." (PMID 39971779, 2025). "Additionally, protein-protein interactions between EZH2 and SMARCB1 have been identified in eosinophilic leukemia cells, corroborating our findings in lung cancer." (PMID 39971779, 2025). "Notably, the increase of SMARCB1 protein levels contrasts with the findings observed in the lung cancer A549 cells." (PMID 39971779, 2025). "Furthermore, in rhabdomyosarcoma, evidence indicates a protein-protein interaction between members of mSWI/SNF (SMARCA2) and GLI-1, consistent with our findings in lung cancer, where SMARCB1 interacts with GLI-1." (PMID 39971779, 2025).
lung carcinoma (continued). "Here, we found that all of the CTC positive patients had SMARCB1 gene mutations in the CTC genome, suggesting that SMARCB1 may have a relationship in the early stage of lung cancer." (PMID 28842574, 2017). "LncRNA AATBC, lncRNA Sirt1-AS, and SMARCB1 may be valuable prognostic biomarkers for lung cancer." (PMID 39313797, 2024). "On the other hand, patients with lung cancer had statistically positive correlations between each of lncRNA GIAT4RA, lncRNA AATBC, lncRNA Sirt1-AS, and SMARCB1 except between lncRNA AATBC, and lncRNA Sirt1-AS (P = 0.074)." (PMID 39313797, 2024). "Homozygous deletions of SMARCB1 are found only in brain cancers, while homozygous deletions of TET1 were almost exclusively observed in lung cancer (seven out of eight cases)." (PMID 29089486, 2017). "Moreover, in MRT, evidence indicates that SMARCB1 interacts with CBP, aligning with our observations in lung cancer." (PMID 39971779, 2025). "Additionally, SMARCB1 functions as a tumor suppressor by regulating EGFR gene expression and modulating cellular response to EGFR-TKIs in human lung cancer." (PMID 39971779, 2025). "Additionally, this regulation involves chromatin remodeling proteins, such as SMARCB1, which binds to EGFR gene regulatory sequences, further shaping its expression and contributing to lung cancer progression." (PMID 39971779, 2025). "In conclusion, our results suggest novel molecular mechanisms whereby MEOX2 and GLI-1 may modulate functional dynamics between cBAF (SMARCB1) and ncBAF (BRD9) complexes, contributing to lung cancer progression." (PMID 39971779, 2025). "Clinical analysis of SMARCB1 in a TCGA lung cancer dataset revealed that low SMARCB1 expression did not affect PFI in non-TKI-treated patients." (PMID 39971779, 2025). "Furthermore, poor survival in patients with lung cancer was indicated by high expression of lncRNA AATBC, SMARCB1, and concentration of NSE." (PMID 39313797, 2024). "LncRNA AATBC, lncRNA Sirt1-AS, SMARCB1, and NSE could be valuable prognostic biomarkers for lung cancer patients." (PMID 39313797, 2024). "Therefore, by use of shSMARCB1, we downregulated SMARCB1 genetic expression and protein levels, identifying a significant decrease in MEOX2 expression and protein levels in A549 lung cancer cells." (PMID 39971779, 2025). "Results showed a significant decrease in EGFR, CBP, and SMARCB1 at mRNA and protein levels, and a significant increase in mRNA of EZH2, but no significant change in protein levels for EZH2, suggesting that both MEOX2/GLI-1 modulate these tumor and epigenetic markers in lung cancer A549 cells." (PMID 39971779, 2025). "Overall, these findings suggest an oncological potential of SMARCB1 as a prognosis biomarker for EGFR-TKI-based therapy responsiveness in lung cancer, uncovering its in vivo function as a tumor suppressor gene and a significant epigenetic actor in human lung cancer progression." (PMID 39971779, 2025). "Nevertheless, higher SMARCB1 expression correlated with significant extended PFIs in TKI-treated early-stage patients compared to lower levels, consistent with studies linking mSWI/SNF subunit alterations to reduced progression-free survival in EGFR-TKI therapy for lung cancer." (PMID 39971779, 2025). "Sucrose Non-Fermenting Gene Number 5 (SNF5, also called SMARCB1, BAF47, INI1) was not inactivated in lung cancers and its functions were need to further confirmation." (PMID 35506290, 2022).
lymphoma (18 papers, 2012 to 2025). A malignant (clonal) proliferation of B- lymphocytes or T- lymphocytes which involves the lymph nodes, bone marrow and/or extranodal sites. "Although loss of SMARCB1 in adult mice leads to lymphoma, SMARCB1 mutation-associated pediatric AT/RTs are found in the CNS, a finding that has been recapitulated in a conditional SMARCB1 KO mouse model." (PMID 31033435, 2019). "This lymphoma phenotype is, however, fundamentally different from any SMARCB1-deficient tumours observed in Humans." (PMID 26818002, 2016). "While this model demonstrates the potent tumor-suppressive function of SMARCB1, the resulting lymphomas do not offer a faithful model for most human SMARCB1-deficient cancers." (PMID 35892904, 2022). "The unexpected development of lymphomas may have been due to reduced knockout efficiency in the adult brain or kidney and the late developmental stage at which Smarcb1 deletion was induced." (PMID 35892904, 2022). "SMARCB1 was first confirmed as a potent in vivo tumor suppressor when a conditional gene knockout of Smarcb1 led to fully penetrant cancer formation in adult mice, resulting in CD8+ mature lymphoma." (PMID 35892904, 2022).